H19 (H19 imprinted maternally expressed transcript)
Diseases named in the same sentence as H19 in open-access papers (continued):
Sharing a sentence is not in itself a finding about the gene and the disease.
ischemic stroke (continued). "For example, H19 is a long ncRNA (lncRNA) that induces the onset of ischemic stroke and participates in the chronic regeneration process following ischemic stroke." (PMID 35055089, 2022). "As such, the combinational roles of neutrophilic miRNA-23a, miRNA-99a, and lncRNA H19 on the ischemic stroke are worth further investigation." (PMID 36278201, 2022). "H19 and miR‐29b expression in leukocytes of patients with ischemic stroke and rats with middle cerebral artery occlusion were measured by real‐time polymerase chain reaction." (PMID 35322553, 2022). "According to a report, H19 levels increase in the circulating blood after ischemic stroke, which promotes the release of inflammatory factors." (PMID 35322553, 2022). "There is altered leukocyte expression of multiple ncRNAs in patients with ischemic stroke, including H19, which is crucially involved in the inflammatory response of ischemic stroke." (PMID 35322553, 2022). "This study aimed to elucidate the inflammatory mechanism of lncRNA H19‐mediated regulation of C1QTNF6 by sponging miR‐29b in leukocytes during ischemic stroke." (PMID 35322553, 2022). "After matching ischaemic stroke-related lncRNAs with berberine-related lncRNAs, four genes (H19, HOTAIR, CASC2, and LINC00943) were selected as potential targets for berberine in the treatment of ischaemic stroke." (PMID 35815278, 2022). "This suggests that H19 is involved in the inflammatory attack in the acute phase of ischemic stroke." (PMID 36275741, 2022). "In clinical experiments, H19 levels were identified to be significantly increased in the plasma at 3 h, 7, 30, and 90 days post-ischemic stroke." (PMID 35055089, 2022). "In ischemic stroke mice, H19 siRNA decreases cerebral ischemic injury and attenuates neurological deficits." (PMID 34675776, 2021). "H19 is an independent risk factor for aspirin resistance (OR=1.129, p=0.0321), and aspirin resistance and H19 are closely related with ischemic stroke recurrence." (PMID 33101034, 2020). "In consistence with these findings, H19 induced neuronal death by activating autophagy in ischemic stroke." (PMID 33613191, 2020). "A previous study was performed on the plasma samples from patients with ischemic stroke, and up-regulated levels of lncRNAs including H19, MIAT, ANRIL, MEG3 and NEAT1 were detected." (PMID 33613191, 2020). "A previous study has indicated that H19 can target ACP5 protein directly and is a putative risk factor of ischemic stroke." (PMID 33613191, 2020). "In the present study, we first demonstrated that H19 level was significantly elevated in ischemic stroke patients, in-vivo MCAO/R animal model and in-vitro OGD neuronal cell model." (PMID 31170091, 2019). "Quantitative real-time polymerase chain reaction (qRT-PCR) revealed that H19 was expressed at low level in the plasma of normal control patients, but it was significantly upregulated in ischemic stroke patients (p<0.05)." (PMID 31170091, 2019). "Mechanistically, H19 promotes neuroinflammation by driving HDAC1-dependent M1 microglial polarization, suggesting a potential novel H19-based diagnosis and therapy for ischemic stroke." (PMID 30967760, 2019). "Among the upregulated genes, Hspa1b, Ccl2, Cxcl2, Ccl3, Serpina3n, Timp1, H19, Hspb1, Ccl20, and Cxcl1 were found to demonstrate significant upregulation in pathological phase of ischemic stroke." (PMID 25861363, 2015). "Moreover, patients with elevated levels of circulating H19 have a worse prognosis after ischemic stroke." (PMID 37628760, 2023). "Also, the association between H19 and the risk of symptomatic ICH in ischemic stroke patients treated with recombinant tissue plasminogen activator was established." (PMID 37377769, 2023). "The lncRNA H19/EGFR/JNK1/c-Jun signalling pathway may be a key mechanism of berberine-induced neuroprotection in ischaemic stroke." (PMID 35815278, 2022). "H19-upregulated Acid Phosphatase 5 induces AS and ischemic stroke." (PMID 34923910, 2022).
ischemic stroke (continued). "In addition, H19 has been shown to promote M1 microglia polarisation and induce neuroinflammation in ischemic stroke by regulating histone deacetylases." (PMID 35055089, 2022). "We further evaluated their correlation using the MNDR3.1 database and found that lncRNA H19 may be the crucial regulatory lncRNA of berberine against ischaemic stroke." (PMID 35815278, 2022). "After ischemic stroke, the lncRNA H19 level in microglial cells was elevated, and the decrease in lncRNA H19 could prevent cells from inflammatory damage." (PMID 33708438, 2021). "In addition, the lncRNA H19 enhances neuroinflammation by driving HDAC1-dependent microglial M1 polarization during ischemic stroke." (PMID 34410604, 2021). "In ischemic stroke, H19 promotes M1 microglial polarization, which results in neuroinflammation." (PMID 33193379, 2020). "H19 also prevents the neurogenesis process after an ischemic stroke event." (PMID 33101034, 2020). "High expression of H19 induces neuroinflammation and autophagy in ischemic stroke." (PMID 33321920, 2020). "Since almost all the patients consume aspirin after an ischemic stroke event, those with high plasma H19 levels might have had aspirin resistance and finally shown a bad prognosis or ischemic stroke recurrence." (PMID 33101034, 2020). "Recent studies have demonstrated a similar elevated H19 levels following ischemic stroke, however, the exact role of H19 in the ischemic brain remains unclear." (PMID 31170091, 2019). "Taken together, these results suggest that H19 might be a potential therapeutic target in ischemic stroke." (PMID 30967760, 2019). "Therefore, we assessed the association between H19 and MALAT1 gene polymorphisms and susceptibility to ischemic stroke in a northern Chinese Han population." (PMID 30305120, 2018). "Taken together, the results of present study suggest that LncRNA H19 could be a new therapeutic target of ischemic stroke." (PMID 28203482, 2017). "LncRNA H19 is therefore a potential genetic marker and therapeutic target of ischemic stroke." (PMID 28203482, 2017). "Thus, it is more likely that rs217727 increases the onset of ischemic stroke through regulation of lncRNA H19 expression." (PMID 28203482, 2017). "Moreover, diminishing lncRNA H19 expression and inhibiting autophagy prevented OGD/R-induced cell death, proposing that lncRNA H19 overexpression and autophagy activation could stimulate cellular apoptosis during ischemic stroke." (PMID 39021183, 2024). "H19 was observed to be one of the most stable lncRNAs in the gray matter of human brain and was extensively studied in the development and diseases of the central nerve system, including ischemic stroke, glioma, pituitary adenoma, neuroblastoma, degeneration, and trauma." (PMID 37377769, 2023). "Finally, in vitro experiments confirmed that berberine may have a good therapeutic effect on ischaemic stroke by regulating the lncRNA H19/EGFR/JNK1/c-Jun signalling pathway." (PMID 35815278, 2022). "Therefore, reducing H19 can suppress neuroinflammation in ischemic stroke." (PMID 36275741, 2022). "Therefore, we hypothesized that C1QTNF6 in leukocytes might be regulated by H19 and miR‐29b that are probably involved in the pathogenesis of ischemic stroke." (PMID 35322553, 2022). "Therefore, H19 reduction can inhibit neuroinflammation in ischemic stroke." (PMID 34675776, 2021). "Therefore, the inhibition of H19 may improve the prognosis of ischemic stroke by promoting the polarization of microglia to M2-like and reducing neuronal apoptosis." (PMID 34707480, 2021). "Also, H19, another lncRNA, is closely related to cell apoptosis after ischemic stroke." (PMID 34707480, 2021). "Moreover, H19 would be a promising biomarker to diagnose ischemic stroke." (PMID 34675776, 2021). "Besides which, H19 may serve as a serological marker for diagnosing aspirin resistance with high specificity and sensitivity, and the test of H19 could give clues to the recurrence of ischemic stroke." (PMID 33101034, 2020).
ischemic stroke (continued). "H19 may be a new target for the treatment of ischemic stroke." (PMID 30778327, 2019). "Early studies have found H19 may suppress tumorigenesis through its long noncoding RNA, but recent research reveals the relationship between H19 and neuroinflammation in ischemic stroke." (PMID 29651234, 2018). "H19 gene polymorphism in ischemic stroke patients has never been examined." (PMID 28203482, 2017). "For example, after ischemic stroke, OGD (oxygen–glucose deprivation) induces upregulation of lncRNA H19, which competes for binding with miR‐423‐5p to regulate NOD‐like receptor protein 3 (NLRP3), promoting inflammatory response and inhibiting neurogenesis." (PMID 40346986, 2025). "A previous study demonstrated a significant positive correlation between circulating H19 levels and the National Institute of Health Stroke Scale (NHISS) scores of patients, observed at 7, 30, and 90 days post‐ischemic stroke." (PMID 39161158, 2024). "Recent studies have identified several lncRNAs that modulate autophagy in ischemic stroke, including MALAT1, MIAT, SNHG12, H19, AC136007." (PMID 39021183, 2024). "Multiple studies reported differential expression of lncRNAs H19, GAS5, PVT1, TUG1, and MALAT1 in ischemic stroke." (PMID 39766887, 2024). "This study aimed to elucidate the inflammatory mechanism of long non‐coding RNA (lncRNA) H19‐mediated regulation of C1q and tumor necrosis factor 6 (C1QTNF6) by sponging miR‐29b in leukocytes during ischemic stroke." (PMID 35322553, 2022). "We previously reported that H19 increases the immune response by increasing plasma TNF‐α and IL‐1β levels after ischemic stroke; moreover, it affects the subsequent pathological outcome." (PMID 35322553, 2022). "The expression level of H19 was significantly increased in MCAO, OGD and OGD/R models, and it was involved in the pathophysiological process of ischemic stroke through processes involving neuronal apoptosis, neuroinflammation, and neurogenesis." (PMID 36275741, 2022). "Current research has discovered the role of certain functional ncRNAs such as lncRNA H19 and MALAT1 in ischemic stroke." (PMID 36132228, 2022). "In summary, this is the first study to demonstrate H19 and C1QTNF6 upregulation and miR‐29b downregulation in leukocytes of patients with ischemic stroke and MCAO rats." (PMID 35322553, 2022). "We confirmed that berberine has an excellent neuroprotective effect via regulation of the lncRNA H19/EGFR/JNK1/c-Jun pathway in hypoxia-induced SH-SY5Y cell injury, making it a possible drug candidate for ischaemic stroke." (PMID 35815278, 2022). "Long noncoding RNA H19 promotes neuroinflammation by driving HDAC1-dependent M1 microglial polarization, suggesting a novel H19-based diagnosis and therapy for ischemic stroke." (PMID 33815877, 2021). "A previous study also indicated that H19 promoted neuroinflammation by M1 microglial polarization, which lead to increased production of TNF-α and IL-1β in ischemic stroke." (PMID 33613191, 2020). "Although we have discovered some functional lncRNAs such as H19 and MALAT1 in ischemic stroke, however, the exploration of lncRNAs still faces multiple challenges." (PMID 29651234, 2018). "Both H19 and MALAT1 have complex regulatory mechanisms in ischemic stroke and evidences are emerging." (PMID 29651234, 2018). "Silencing of H19 significantly decreased the cerebral infarct volume, enhanced the recovery of neurological function, mitigated BBB damage, and stimulated endothelial cell proliferation following ischemic stroke." (PMID 39161158, 2024). "Since the relationship between H19 and aspirin resistance have never been reported, herein, we aimed to evaluate the H19 expression in aspirin-resistant ischemic stroke patients and subsequently, ascertain the ability of H19 to diagnose aspirin resistance." (PMID 33101034, 2020).
Wilms tumor (45 papers, 2004 to 2025). An embryonal neoplasm characterized by the presence of epithelial, mesenchymal, and blastema components. "In all seven samples from the child’s tumour, we found a likely disruptive somatic CTCF variant of the remaining allele and detected associated hypermethylation of H19 (thought to be the Wilms tumour promoting effect of CTCF loss)." (PMID 39665570, 2025). "The IC1 (H19 gene) hypermethylation of chromosome 11p15 increases the risk for Wilms tumor due to the biallelic expression of the IGF2 gene." (PMID 37052241, 2023). "It is worth mentioning here that BWS patients with the gain of methylation in H19 TSS DMR have a risk of Wilms tumor development." (PMID 30898153, 2019). "In addition to epigenetic alterations, genetic alterations, such as the amplification of paternal alleles leading to overexpression of IGF2 and LOH of the maternal allele leading to reduced expression of H19, were observed in sporadic Wilms’ tumors." (PMID 24373183, 2013). "This may indicate that either the risk of Wilms tumor is higher in H19 epimutation than in pUPD 11p15 tumors and/or that H19 epimutation is more likely to occur earlier in embryogenesis and hence be present in both kidneys." (PMID 22470196, 2012). "Neuroblastoma may also demonstrate 14q allele loss and Wilms' tumour was of interest as epigenetic alterations at the IGF2/H19 locus are common in this tumour." (PMID 15798773, 2005). "In addition, epigenetic alterations at IGF2 and H19 have been implicated in the pathogenesis of sporadic childhood (e.g. Wilms' tumour) and adult (e.g. colorectal) cancers." (PMID 15798773, 2005). "Although H19 is upregulated in most tumor cells, H19 is downregulated in isolated cancer types such as nephroblastoma." (PMID 38355574, 2024). "Lower gene expression levels of lncRNAs H19 and miR-675 (p < 0.05) were observed in nephroblastoma cells, followed by higher gene expression levels of TGFBI than that in normal cells." (PMID 38355574, 2024). "It was recently discovered in nephroblastoma cells that lncRNA H19 significantly influences the miR-675/TGFBI axis to enhance proliferation and prevent apoptosis." (PMID 37964955, 2023). "A loss of heterozygosity (i.e., loss of the maternal allele) or loss of imprinting at the H19/IGF2:IG-DMR (i.e., biallelic expression of IGF2) in Wilms’ tumors was subsequently demonstrated by several teams." (PMID 35741015, 2022). "Patients with H19/IGF2:IG-DMR hypermethylated present Wilms tumor and hepatoblastoma their recurrence is related to IGF2 overexpression during cancer development." (PMID 33101381, 2020). "The overall tumor risk of H19/IGF2:IG-DMR GOM is ∼23%, specifically with a 21% risk of developing Wilms tumor." (PMID 33101381, 2020). "Wilms tumor rate is more frequent in the H19/IGF2:IG-DMR subgroup than in the cases observed for the UPD." (PMID 33101381, 2020). "Igf2 upregulation along with the neighboring gene H19 is particularly interesting as IGF2 is recognized be one of the most important Wilms tumor oncogenes." (PMID 30635573, 2019). "IGF2 LOI in Wilms tumor and hepatoblastoma is reportedly correlated with hypermethylation of H19-DMR, which is the ICR in the IGF2/H19 domain." (PMID 30509319, 2018). "It has been suggested that H19 functions as a tumor suppressor in some Wilms' tumors, embryonic rhabdomyosarcoma, and the Beckwith-Wiedmann cancer predisposing syndrome." (PMID 24466011, 2014). "Hypermethylation at H19-DMR and the H19 promoter also reduced the expression of H19 in Wilms’ tumor." (PMID 24373183, 2013). "Hypermethylation at H19 DMR has been associated with a remarkable down-regulation of H19 expression, loss of imprinting of IGF2, and several disorders, including Wilm's tumors in children; a cancer type that is more prevalent in African Americans." (PMID 22414206, 2011).
Wilms tumor (continued). "Although de novo methylation and silencing of H19 in Wilms' tumours was first reported some years ago, epigenetic changes have not been investigated in great detail in Wilms' tumour." (PMID 14735202, 2004). "For instance, children with bilateral Wilms tumor often exhibit H19 hypermethylation." (PMID 38893137, 2024). "H19 inhibits growth and induces morphological changes in nephroblastoma cells." (PMID 38355574, 2024). "However, other studies have demonstrated the tumor suppressor function of H19 in Wilms tumor and rhabdomyosarcoma." (PMID 39659621, 2024). "H19-DMR hypermethylation leads to IGF2 LOI and H19 silencing in Wilms tumor and hepatoblastoma." (PMID 30509319, 2018). "Moreover, the H19 gene is frequently inactivated in Wilms tumor." (PMID 17786216, 2007). "In Wilms' tumours, mutation of the Wilms tumour 1 (WT1) gene at the WT1 locus has been reported, and the WT2 locus, comprising the two independent imprinted domains IGF2/H19 and KIP2/LIT1, can undergo maternal deletion or alterations associated with imprinting." (PMID 16909133, 2006). "Downregulation of H19 suppresses TGFBI expression by regulating miR-675 levels, thereby promoting apoptosis in nephroblastoma cells." (PMID 38355574, 2024). "In a study of 70 BWS and 2 SRS patients, the methylation patterns at the IGF2 DMR0 resembled that at the H19 DMR, in contrast to 33 non-syndromic Wilms tumours in which IGF2 DMR0 methylation was negatively correlated with H19 DMR methylation." (PMID 22646060, 2012). "Considering the absence of H19 in embryonic rhabdomyosarcoma and Wilms’ tumor, H19 is thought to function as a tumor suppressor." (PMID 35565245, 2022). "Wilms tumor represents the most common cancer in BWS patients with a high prevalence in combination with telomeric defects in H19/IGF2:IG-DMR -GOM and UPD subgroups (21.1% vs. 6.2%, respectively, P < 0.001); subjects with centromeric defects display a lower rate." (PMID 33101381, 2020). "Furthermore, loss of heterozygosity or imprinting on chromosome 11p15, which harbors a cluster of imprinted genes, is documented in approximately 70% of Wilms tumors, resulting in biallelic expression of IGF2 and its neighboring H19 gene." (PMID 30635573, 2019). "In Wilms’ tumors, reduced expression of lncRNA KCNQ1DN existing far from the H19/IGF2 region and may play regulatory role in tumor progression." (PMID 31001325, 2019). "Therefore, we examined the allelic expression of H19 and IGF2, genes known to be aberrantly imprinted in some Wilms tumours." (PMID 29912901, 2018).